LEP (leptin)
Diseases named in the same sentence as LEP in open-access papers (continued):
Sharing a sentence is not in itself a finding about the gene and the disease.
Insulin resistance (continued). "In this regard, the reduced energy expenditure and increased BMI detected in the obese mice may be related to both insulin resistance and impaired leptin action." (PMID 30030460, 2018). "Based on these association studies like these, if leptin action is involved in OSA, then the involvement of other endocrine systems including sex-hormones and insulin resistance may be important co-contributors to OSA." (PMID 30127766, 2018). "Therefore the aim of this study was to evaluate some probable predictors of MS, such as leptin and adiponectin concentrations, the leptin/adiponectin ratio, insulin resistance, and adiposity, in a sample of child survivorsof ALL and lymphoma." (PMID 28193268, 2017). "An interesting hypothesis, which would be in agreement with our findings, is that PF affects “leptin resistance” where high plasma leptin levels coexist with late satiety and insulin resistance." (PMID 28609470, 2017). "Among RA-related risk factors, proinflammatory cytokines (TNF-α, IL-6), oxidative stress, an increase of leptin and resistin (proatherogenic hormones) and the decrease of adiponectin (antiatherogenic hormone), and insulin resistance play the most important role in accelerated atherogenesis." (PMID 29200598, 2017). "The 4-week very-low calorie diet (VLCD, 800 kcal/day) induced a mean weight loss of 6.9 ± 1.9 kg accompanied by a reduction in HOMA-IR (Homeostasis model assessment-insulin resistance), fasting plasma glucose and insulin, plasma leptin, and leptin gene expression in subcutaneous adipose tissue." (PMID 28931850, 2017). "Therefore, leptin and adiponectin were included in a multivariate linear regression model to identify the most important factors influencing the relationship between insulin resistance and hot flashes." (PMID 28448547, 2017). "Moreover, the adiponectin/leptin ratio has been suggested as a maker of adipose tissue dysfunction and correlates with insulin resistance more closely than adiponectin or leptin alone or even HOMA, a surrogate of insulin resistance." (PMID 28747790, 2017). "It should be pointed out that serum adiponectin and leptin were no longer significantly associated with β-cell function when insulin resistance was additionally controlled for in the multiple linear regression analysis." (PMID 28786989, 2017). "Leptin may contribute to insulin resistance and its metabolic correlates and appears to have a direct pro-thrombotic effect, in addition to acting synergistically with insulin and free fatty acids to stimulate sympathetic activity and vasoconstriction." (PMID 27598976, 2017). "In the present study, we investigated the effects of BTS on the mRNA expression levels of UCP1, adiponectin, and leptin in adipose tissue, as well as insulin resistance, serum triglycerides, white adipocyte size, and white adipose tissue weight in high-fat diet-fed obese model mice." (PMID 28360931, 2017). "Further, ASH ameliorated leptin and insulin resistance and prevented HFD-induced apoptosis." (PMID 29025435, 2017). "In addition, GlycA is positively correlated with body mass index (BMI), insulin resistance, markers of metabolic syndrome, and the ratio of leptin to adiponectin, suggesting that it is related to adipose tissue-associated low-grade inflammation." (PMID 28642810, 2017). "High leptin concentration, low-grade inflammation, and insulin resistance often coexist in obese subjects; this adverse metabolic milieu may be the main culprit for increased fracture risk and impaired bone quality seen in patients with type 2 diabetes." (PMID 28640843, 2017). "In the present study, BTS improved insulin resistance and reduced serum leptin." (PMID 28360931, 2017). "To find the relationship between exercise training and SP-D in diabetes, we examined the possible effects of a 10-week endurance exercise-training program on serum levels of SP-D, leptin, lipid profile and insulin resistance in obese women with type-2 diabetes mellitus (T2DM)." (PMID 29021828, 2017).
Insulin resistance (continued). "Leptin enhances peripheral insulin sensitivity and improves pancreatic β-cell function.These normal functions of leptin are disrupted in leptin resistance state of pregnancy inducing insulin resistance and impaired glucose tolerance in pregnancy." (PMID 28732072, 2017). "The implication of leptin in insulin resistance of PCOS is still unclear." (PMID 27473078, 2017). "Although experimental studies have shown that adiponectin and leptin modulate glucose tolerance and insulin resistance, it remains unclear whether these adipocytokines exert similar effects in general human populations." (PMID 28786989, 2017). "Leptin, in turn, was a strong positive correlate of insulin resistance and β-cell function." (PMID 28286536, 2017). "The HOMA‐IR index 48 and the leptin/adiponectin ratio 49 are markers for insulin resistance." (PMID 28211258, 2017). "Likewise, cellular insulin resistance disrupts leptin-mediated control of neuronal signaling and transcription." (PMID 28270795, 2017). "Leptin is released in obesity in response to accumulating subcutaneous fat and increased fatty acid oxidation, a phenomenon regarded as a state of higher insulin resistance." (PMID 29104874, 2017). "Indeed, pharmacological or genetic induction of ER stress in the hypothalamus has been shown to lead to leptin and insulin resistance, resulting in increased energy intake, hypertension, and insulin tolerance." (PMID 28798799, 2017). "Moreover, TRR treatment improved glycemic control and with favorable lipid profiles, implying that these favorable effects of TRR with adiponectin and leptin levels confers a protective effect on insulin resistance." (PMID 29099085, 2017). "Furthermore, a significant relationship was found between the rs7566605 and insulin, homeostasis model of assessment-insulin resistance, the percentage of body fat, fat mass, leptin, and adiponectin." (PMID 28160769, 2017). "Moreover, the ratio of leptin to adiponectin is suggested to be a useful index of insulin resistance and a good indicator of anti-diabetic therapy effectiveness as well as a potential biomarker for atherosclerosis in obese T2DM." (PMID 29295491, 2017). "Finally, cholecalciferol supplementation in children was shown to decrease the value of the leptin-to-adiponectin ratio (L/A), a marker of metabolic disease, which is better correlated with insulin resistance than the levels of each single peptide." (PMID 28475159, 2017). "However, inactivation of SOCS3 in ObRb-expressing cells protects mice from diet-induced insulin resistance, indicating that the regulation of leptin signaling by SOCS3 orchestrates diet-induced changes on glycemic control." (PMID 28270795, 2017). "This increase in leptin to adiponectin ratio seemed to contribute to the observed effect of deworming on increased insulin resistance (IR) as adjustment for leptin to adiponectin ratio attenuated the effect on IR from 1.07 (1.01–1.14, P=0.023) to 1.05 (0.99–1.11, P=0.075)." (PMID 29035384, 2017). "This was accompanied by an increase in epididymal fat weight per body weight, plasma levels of triglycerides and leptin together with the development of hyperglycemia, hyperinsulinemia, insulin resistance, hypertension and allodynia, a feature of neuropathic pain." (PMID 29165388, 2017). "Leptin secretion could be regulated by the accumulation of fat in adipocytes, which resulted in insulin resistance as observed in the obese animal model." (PMID 27058520, 2016). "However, it induced insulin resistance, increased plasma levels of cholesterol, triglycerides and leptin only after 60 days of fructose consumption." (PMID 27930685, 2016). "In addition, inflammation induced upregulation of SOCS-3, a marker of leptin and insulin resistance, can result in impaired ability of satiety signals, such as cholecystokinin, to activate neurons in the hindbrain and reduce food intake." (PMID 27512604, 2016).
Insulin resistance (continued). "Additionally, clinical data have shown that other cytokines, such as TNF-α, leptin, and adiponectin, are also involved in insulin resistance." (PMID 27110299, 2016). "Indeed, an increase in central leptin is reported to reverse hepatic insulin resistance and to correct peripheral glucose usage." (PMID 26937247, 2016). "In our study population, malnutrition was associated with a nearly three-fold decrease in serum leptin levels despite an absence of differences in cytokine profiles, adipokine levels, gut hormone concentrations, or insulin resistance." (PMID 27583675, 2016). "Serum leptin, which is a cytokine-like hormone predominantly produced in the white adipose tissue and secreted into the systemic circulation, was positively correlated with markers of insulin resistance." (PMID 27534844, 2016). "It is concluded from these depletion states in leptin levels that insulin resistance and hyperinsulinaemia, hyperglycaemia, dyslipidaemia and visceral adiposity could also be related to leptin action." (PMID 27147943, 2016). "Leptin stimulates insulin resistance whereas adiponectin elevates insulin sensitivity." (PMID 27122001, 2016). "Angiotensin II promotes the growth and differentiation of adipocytes, the decrease in plasma adiponectin levels and increase of insulin resistance, induces the expression of C-reactive protein, and results in the secretion of leptin, which in turn activates the renal sympathetic nerve." (PMID 26911143, 2016). "A number of mechanisms have been proposed to explain leptin and insulin resistance." (PMID 27812350, 2016). "Leptin, adiponectin, and resistin are peptide hormones, which might have a potential role in the mechanism leading to insulin resistance." (PMID 27212946, 2016). "We found that the extracts blocked the increase of fasting blood glucose, serum triglyceride (TG), insulin, leptin, and liver lipid levels and prevented the development of glucose tolerance impairment and insulin resistance in the C57BL/6 mice induced by a high-fat diet." (PMID 27088095, 2016). "The effects of Z-551 were examined in wild type mice on HFD and it could suppress body weight gain, ameliorated insulin resistance and abnormal lipid metabolism, significantly reducing the plasma levels of glucose, FFAs, insulin and leptin." (PMID 27483259, 2016). "Compared with leptin or leptin receptor mutated diabetic animal model, our model showed the superiority by endowing animal typical insulin resistance without the interference of leptin deficiency on healing." (PMID 27028201, 2016). "Furthermore, a study showed that the plasma levels of glucose, leptin, insulin, total cholesterol, and triglyceride were lowered in high-fat diet mice treated with Ergostatrien-3β-ol from A. camphorata, and insulin resistance was also attenuated in these mice." (PMID 27047382, 2016). "Hyperthyroid patients presented with significantly lower serum levels of high-density lipoprotein cholesterol, LDLC and leptin, as well as higher levels of fasting insulin, resistin, adiponectin and homeostasis model insulin resistance index (HOMA-IR) than control (p < 0.05)." (PMID 27193069, 2016). "The effects of ω-3 PUFA overload on the prevention of weight gain excess and the development of insulin resistance may be mediated by adiponectin and leptin, two adipokines that regulate glucose and lipid metabolism, through AMPK activation." (PMID 26901315, 2016). "Markers of microbial fermentation of FOPS, including total SCFA, acetate, and cecal weight were negatively correlated with many host metabolic markers, including body weight gain, fasting glucose, fasting insulin, index of insulin resistance, C-peptide, adipose tissue weights, resistin, and leptin." (PMID 26731528, 2016). "Induction of SOCS3 and reduction of oxytocin expression might explain leptin and insulin resistance as well as hyperphagia that are observed in CMHL rats already 7 d post-surgery and that are also key clinical features in CP patients." (PMID 27512604, 2016).
Insulin resistance (continued). "Thus, quercetin suppresses the accumulation and activation of immune cells and the subsequent inflammation and systemic insulin resistance, probably by suppressing the expression of leptin, TNFα, and possibly IFNγ." (PMID 26499876, 2016). "Serum leptin seems to have an association with NAFLD both in male and female prediabetic subjects and this association in turn, is mediated by insulin secretory dysfunction and insulin resistance among these subjects." (PMID 26569494, 2015). "Leptin and adiponectin represent the most abundant adipokines in human plasma that play crucial roles in the pathophysiology of metabolic syndrome, atherosclerosis and insulin resistance." (PMID 26869871, 2015). "Interestingly, leptin was recommended as a biomarker for in utero insulin resistance based on the link between maternal and fetal leptin and IR." (PMID 26136779, 2015). "The physiological effect of SSB consumption on metabolic abnormalities may be explained by increased lipogenesis, leptin resistance, intra-abdominal fat storage, abnormal glucose level due to insulin resistance, and high blood pressure." (PMID 26729156, 2015). "In obese and insulin-resistant mice, leptin levels increase due to leptin resistance." (PMID 25918733, 2015). "Besides typical insulin resistance signs, EC patients with SO often display a higher serum leptin/adiponectin ratio compared with MHO patients." (PMID 28031919, 2015). "Firstly, leptin is inextricably related to insulin resistance." (PMID 26569494, 2015). "It has been suggested that leptin may contribute to hepatic steatosis by promoting insulin resistance and by altering insulin signaling in hepatocytes, so as to promote increased intracellular fatty acids." (PMID 26569494, 2015). "Because of increasing serum leptin and increasing insulin resistance after COH, the incidence of PE could be higher." (PMID 26000008, 2015). "Since exercise training beneficially affects insulin resistance, mechanisms involved in leptin responses might be related." (PMID 25885799, 2015). "Studies have shown that both a lack of leptin signals and adiposity as such may contribute to insulin resistance and that decrease in central leptin signaling can critically affect glucose metabolism in obese mice." (PMID 26347815, 2015). "A comparison of maternal and fetal insulin resistance and leptin between female and male offspring." (PMID 26368559, 2015). "Our study results revealed that 1) In male prediabetic subjects, insulin resistance was independently associated with serum leptin levels irrespective of adiposity and glycemic status." (PMID 26569494, 2015). "An analysis of 13 murine models of lipodystrophy identified the reduction in fat pad mass, elevated TG, insulin resistance, elevated blood glucose, liver steatosis, and the decreased production of leptin and adiponectin as some of the features of the various lipodystrophic mouse models." (PMID 26536476, 2015). "Follow-up studies of this and similar cohorts may in time reveal if statistical differences in leptin and insulin resistance translate into clinically meaningful outcomes." (PMID 26368559, 2015). "Common features of childhood obesity are elevated leptin levels and insulin resistance." (PMID 26447698, 2015). "Betatrophin did not correlate with BMI or insulin resistance but showed a weak association with leptin levels in pregnancy and negative relationship with fasting C-peptide levels in all women." (PMID 26325425, 2015). "Since leptin stimulates the transcription of genes encoding IR and IRS-proteins, a decrease of its regulatory effects at the early stages of insulin resistance leads to weakening of function of the brain insulin system and exacerbates insulin resistance." (PMID 28031898, 2015). "Leptin and adiponectin show opposite effects on inflammation and insulin resistance." (PMID 26581745, 2015).
Insulin resistance (continued). "Additionally, the evaluation of the leptin: adiponectin ratio has been suggested as a useful parameter for assessing insulin resistance, and is more effective as an insulin resistance parameter than adiponectin or leptin alone." (PMID 26389928, 2015). "Although abdominal obesity is closely associated with insulin resistance (hyperinsulinaemia), hyperleptinaemia and glucose dysfunction, changes in seminal plasma concentrations of insulin, leptin and glucose in obese males has not previously been investigated." (PMID 24885899, 2014). "We have already known that physical activity had several beneficial impacts on type 2 diabetes insulin resistance, and it could produce a similar action on leptin." (PMID 25187423, 2014). "Many factors contribute to fatty liver: methionine-choline deficiency, alcohol, insulin resistance, hepatotoxins, lack of leptin or its receptor." (PMID 25520925, 2014). "This may be reflected by our serial mediation model, where hyperinsulinemia and insulin resistance acted as precursor for higher leptin values, which then together accounted for the relation between VS activity and BMI values." (PMID 25368558, 2014). "In obese hypertensive subjects, changes in serum leptin levels correlated to changes in blood pressure levels after weight loss regardless of insulin resistance confirming the role of leptin in the pathophysiology of hypertension in obese patients." (PMID 24772364, 2014). "Adipokines, such as leptin, adiponectin, and resistin, may also be involved in the pathogenesis of insulin resistance." (PMID 25202741, 2014). "For both of the adipokines; serum resistin and plasma leptin (markers of insulin resistance), there was a significant decrease within the intervention group, but this was not significant compared to the control group, where there also was a (non-significant) decrease." (PMID 25330848, 2014). "Our third hypothesis was also approved, in that the relationship between neural food-related reward processing and body weight was mediated by insulin resistance and leptin." (PMID 25368558, 2014). "We speculate that leptin may play an important role in the development of physiological insulin resistance, which is a major component of metabolic syndrome." (PMID 25214835, 2014). "Due to the common observation of increased leptin values and insulin resistance in obese patients, we hypothesize that these changes are linked to alterations in mesolimbic circuits during anticipatory food reward processing." (PMID 25368558, 2014). "Conversely, peripheral insulin resistance in muscle and adipose tissue could develop via a link to low leptin levels, reduced muscle oxidative capacity, impaired GLUT4 expression, and diminished blood flow in hypothyroidism." (PMID 24872812, 2014). "Similar to leptin effects, resistin seems to mediate insulin resistance." (PMID 25548896, 2014). "In ob/ob mice, lack of leptin results in abnormally high levels of neuropeptide Y and increased cortisol levels, which underlie muscular insulin resistance." (PMID 24809394, 2014). "The causation of these conditions can involve many factors aside from diet including lack of exercise, genetic predisposition to insulin resistance, dysfunction of other hormones (leptin, adiponectic), impaired beta oxidation, hepatotoxins, and some viruses." (PMID 24950438, 2014). "Increased leptin levels may contribute to insulin resistance in GDM and in the third trimester of normal pregnancy." (PMID 25202741, 2014). "Leptin’s involvement in insulin resistance in these rodent models is complex and controversial." (PMID 24809394, 2014). "Insulin resistance, fasting blood glucose, and leptin improved in all groups at 6 and 12 months." (PMID 27433488, 2014). "The results demonstrated a negative association of insulinemia, leptin levels and markers of insulin resistance with BMD, suggesting that the parameters analyzed play a significant role in bone metabolism." (PMID 23743968, 2013).